TRIM21 (tripartite motif containing 21)
Diseases named in the same sentence as TRIM21 in open-access papers (continued):
Sharing a sentence is not in itself a finding about the gene and the disease.
breast carcinoma (continued). "It is notable that TRIM21 expression is up-regulated in a broad spectrum of cancers, including glioma, breast cancer and nasopharyngeal carcinoma (NPC) 27, 46-48." (PMID 38385081, 2024). "To further explore the predictive performance of MTA1, MTA3, and TRIM21 in the prognosis of patients with breast cancer, we performed immunohistochemical staining." (PMID 39154024, 2024). "TRIM21 overexpression inhibited invasiveness, whereas knockdown of TRIM21 promoted invasiveness in breast cancer cells." (PMID 39154024, 2024). "The EdU assays in breast cancer cells showed that the decrease in proliferation mediated by MTA1 knockdown was reversed by MTA3 or TRIM21 knockdown." (PMID 39154024, 2024). "Remarkably, breast cancer cells overexpressing Trim21 exhibited accelerated degradation of the CCT2 protein upon treatment with CHX, implicating Trim21 in modulating CCT2 stability." (PMID 39079960, 2024). "In breast cancer cells, TRIM21 regulates the EMT process by affecting the proteasomal degradation of SNAI1." (PMID 39154024, 2024). "The downregulation of TRIM21/Ro52 is associated with a poor prognosis in patients with certain kinds of cancer, including DLBCL, breast cancer, gastric cancer, renal cell carcinoma, ovarian cancer, and colitis-associated cancer." (PMID 37993883, 2023). "Higher expression of TRIM21/Ro52 is associated with better patient survival in some cancer types, such as diffuse large B-cell lymphoma (DLBCL), breast cancer, and renal cell carcinoma." (PMID 37993883, 2023). "The tumor suppressor role and inner mechanisms of TRIM21 in TNBC or other types of breast cancer should be further verified and elaborated by further experimental evidence and omics analysis." (PMID 37864041, 2023). "TRIM21 expression was reported to be frequently decreased in some types of cancers, including colorectal and breast cancers." (PMID 36749630, 2023). "TRIM21 overexpression is an oncogenic event in many types of cancers, including glioma, breast cancer and others." (PMID 37367937, 2023). "Correlation analysis showed a negative correlation between the cell sensitivity to Olaparib and TRIM21 expression level in breast cancer cell lines (R = −0.65)." (PMID 37864041, 2023). "Knockdown of TRIM21 markedly rescued Snail downregulation by USP41 siRNA in both breast cancer cells." (PMID 36675208, 2023). "In breast cancer, TRIM21 has been indicated as a tumor suppressor or reported to participate in the dysregulation of the oncogenic signaling pathway." (PMID 37864041, 2023). "High expression level of TRIM21 indicated good prognosis in breast cancer, diffuse large B-cell lymphoma and hepatocellular carcinoma 39-41." (PMID 35864951, 2022). "Previous studies found that the overexpression of TRIM21 inhibits tumor migration and invasion in breast cancer cell lines." (PMID 35024438, 2022). "In this study, the prognostic risk model consisting of six ARGs (VPS35, TRIM21, PRKAB2, RUFY4, MAP1LC3A and LARP1) in breast cancer were identified." (PMID 34001111, 2021). "It has been reported that TRIM21 inhibits epithelial-mesenchymal transition (EMT) via Snail ubiquitination in breast cancer cells." (PMID 34001111, 2021). "So far, among these 6 ARGs, Only TRIM21 and MAP1LC3A, as low-risk autophagy-related genes, have been studied in breast cancer or other cancers." (PMID 34001111, 2021). "In conclusion, we identified a novel autophagy-related prognostic risk model consisting of six encoding gene (VPS35, TRIM21, PRKAB2, RUFY4, MAP1LC3A and LARP1) in breast cancer." (PMID 34001111, 2021). "TRIM21 has been demonstrated its anti-oncogenic function in breast cancer and some molecular mechanisms have been revealed." (PMID 34001111, 2021).
breast carcinoma (continued). "Overexpression of TRIM21 in MCF7 breast carcinoma cells increased cell proliferation and colony formation." (PMID 32678213, 2020). "Taken together, our data suggest that SET7/9 has a promoting role via the regulation of RUNX2, whereas TRIM21-mediated SET7/9 degradation acts as an anti-braking system in the progression of breast cancer." (PMID 32102992, 2020). "TRIM21 has also been found to be downregulated at posttranscriptional levels by microRNA miR-494-3p in breast cancer cells." (PMID 32678213, 2020). "Previous reports have suggested that the depletion of TRIM21 in breast cancer cells is correlated with increased cell proliferation and tumor formation." (PMID 32678213, 2020). "Accordingly, the online survival analysis database Kaplan–Meier plotter demonstrated the prognostic value of TRIM21 mRNA in breast cancer according to the mRNA gene chip data." (PMID 32102992, 2020). "In this study, we have shown that TRIM21 enhances the proliferation of MCF7 breast carcinoma cells and counteracts the decrease in cell proliferation and colony formation caused by UV-induced DNA damage." (PMID 32678213, 2020). "Here, we report an increase in the proliferation and colony formation of breast cancer cells as a result of TRIM21 expression." (PMID 32678213, 2020). "Research found that TRIM21 modulated epithelial–mesenchymal transition (EMT) by regulating the stability of Snail in breast cancer." (PMID 33006365, 2020). "Our data provide compelling evidence that the degradation of SET7/9 by TRIM21 can be used to suppress breast cancer progression." (PMID 32102992, 2020). "Although TRIM21 was first identified as a regulator of innate immune signaling, more and more evidences suggested a possible tumor suppressive role of TRIM21 in breast cancer." (PMID 32102992, 2020). "For example, TRIM21 mediates ubiquitination of Snail and modulates epithelial to mesenchymal transition in breast cancer cells." (PMID 31739287, 2019). "Recent studies have also revealed that TRIM21 interacts with snoRNAs in human breast cancer cells." (PMID 40096176, 2025). "In addition, TRIM21 was able to inhibit the expression of malignant transcription factors Sal-like family in breast cancer." (PMID 38720056, 2025). "MTA3 and TRIM21 are potential prognostic biomarkers for breast cancer." (PMID 39154024, 2024). "Low expression of TRIM21 positively correlates with poor prognosis of patients with breast cancer." (PMID 39154024, 2024). "Moreover, CHX chase assays demonstrated that Trim21 overexpression promoted CCT2 protein degradation in breast cancer cells, whereas Trim21 knockdown extended the half-life of the CCT2 protein." (PMID 39079960, 2024). "Recent investigations have revealed diminished TRIM21 expression in breast cancer." (PMID 39556022, 2024). "In addition, TRIM21 is another E3 ligase regulating Snail ubiquitination resulting in the decrease of EMT in breast cancer cells." (PMID 36675208, 2023). "In breast cancer, overexpression of TRIM21/Ro52 promotes ubiquitination and degradation of Snail, resulting in the downregulation of E-cadherin transcription throughout the epithelial–mesenchymal transition process, thereby inhibiting migration and invasion capabilities in breast cancer cells." (PMID 37993883, 2023). "In addition, degradation of spalt-like transcription factor 4 (SALL4), a transcription factor that promotes breast cancer cell proliferation and migration, is regulated by TRIM21/Ro52, and thus higher levels of TRIM21/Ro52 can reduce SALL4 levels." (PMID 37993883, 2023). "Consistently, we found that TRIM21 protein levels were frequently downregulated in colorectal and breast cancers by IHC staining analysis of TRIM21 expression in multiple cohorts of colorectal and breast cancers using tissue microarrays (TMAs; obtained from US Biomax)." (PMID 36749630, 2023). "In addition, the low expression of TRIM21 indicates worse outcome and promotes cell growth in breast cancer." (PMID 34001111, 2021).
breast carcinoma (continued). "For instance, TRIM21 has been demonstrated to be downregulated in hepatocellular carcinoma, breast cancer, and diffuse large B-cell lymphomas, whereas other studies have shown that decreased expression of TRIM21 predicts better prognosis in pancreatic cancer patients." (PMID 33414451, 2021). "Together, these results demonstrated that TRIM21 regulated breast cancer progression via SET7/9." (PMID 32102992, 2020). "However, we found TRIM21 overexpression enhances proliferation as well as colony formation by breast cancer cells." (PMID 32678213, 2020). "The interpretation of TRIM21/SET7/9/RUNX2 axis leads to a deeper comprehend about the molecular properties of breast cancer malignancy, and might be an attractive target for its diagnosis and therapy." (PMID 32102992, 2020). "Research indicates that TRIM21/Ro52 contributes to the pathology of pSS and cancer, with increased expression levels linked to improved survival outcomes in certain cancer types, including diffuse large B-cell lymphoma (DLBCL), breast cancer, and renal cell carcinoma." (PMID 40429494, 2025). "In patients with pancreatic and thyroid cancers, TRIM21 overexpression has been associated with poor prognosis, whereas in patients with diffuse large B-cell lymphoma and ovarian, gastric, and breast cancers, low TRIM21 levels have been linked to negative clinical outcomes." (PMID 40768895, 2025). "Herein, in this review, we summarize current evidence of TRIM21/Ro52 relevant connections to immune regulation and cellular metabolism in SLE, pSS, and cancers, then discuss how TRIM21/Ro52 may function in the tumorigenesis, especially lymphoma and breast cancer in SLE and pSS patients." (PMID 37993883, 2023). "Moreover, TRIM21 is involved in the epithelial to mesenchymal transition in breast cancer cells." (PMID 32678213, 2020). "The findings indicated that MTA1 expression was significantly upregulated in breast cancer tissues compared to that in normal tissues, whereas MTA3 and TRIM21 were the opposite." (PMID 39154024, 2024). "Our results revealed that TRIM21 hindered proliferation, invasion, EMT, and stemness in breast cancer." (PMID 39154024, 2024). "Breast cancer patients with high TRIM21 expression have favorable relapse free survival (RFS) and overall survival (OS) compared with those with low TRIM21 expression." (PMID 39154024, 2024). "In this study, we aimed to investigate the roles of MTA1, MTA3, and tripartite motif-containing 21 (TRIM21) in the proliferation, invasion, epithelial-mesenchymal transition (EMT), and stem cell-like properties of breast cancer cells in vivo and in vitro." (PMID 39154024, 2024). "Our study identified multiple regulators of breast cancer stemness and showed that MTA1 influences the cancer stem-like state by interacting with EMT and inhibiting the expression of MTA3 and TRIM21." (PMID 39154024, 2024). "Estrogen disrupted the balance between MTA1 and MTA3, as well as between MTA1 and TRIM21, thereby affecting stemness and the EMT processes in breast cancer." (PMID 39154024, 2024). "Transfection of FLAG-ERα contributed to the upregulated expression of TRIM21 and MTA3 and led to the decreased expression of MTA1 in breast cancer cells." (PMID 39154024, 2024). "MTA1-overexpression promoted the invasiveness of breast cancer cells, while overexpression of MTA3 or TRIM21 restored it to normal levels." (PMID 39154024, 2024). "In this review, we summarize current findings on how TRIM21/Ro52 affects inflammation and tumorigenesis, and investigate the relationship between TRIM21/Ro52 expression and the formation of lymphoma and breast cancer in SLE and pSS populations." (PMID 37993883, 2023).
breast carcinoma (continued). "qChIP-dependent promoter walk experiments showed that, in breast cancer cells, ERα was mainly enriched in the −800 to −200 section of the TRIM21 promoter, MTA1 was mainly enriched in the −1 400 to −500 region of the TRIM21 promoter." (PMID 39154024, 2024). "TRIM21 is downregulated by MTA1 and plays a vital role in breast cancer." (PMID 39154024, 2024). "Meanwhile, TRIM21 inhibits the transcription of runx family transcription factor 2 (RUNX2) by regulating the degradation of set domain containing 7/9 (SET7/9), thereby inhibiting the malignant phenotype in breast cancer." (PMID 39154024, 2024). "Additionally, we demonstrated that Trim21 modulates CCT2 ubiquitination and degradation, thereby influencing its impact on breast cancer progression." (PMID 39079960, 2024). "Moreover, FASN acetylation enhances its interaction with TRIM21 in HCC, TRIM21 can ubiquitinate and decrease the expression of FASN in breast cancer, and GNPAT inhibits TRIM21-mediated FASN degradation and promotes lipid metabolism." (PMID 37190313, 2023). "Therefore, TRIM21 and PSMD7 play significant roles in the antitumor effect of HTR1A through the TGF‐β pathway in breast cancer cells." (PMID 35199941, 2022). "Strikingly, we identified that SET7/9 was another substrate of TRIM21, by mediating the proteosomal degradation of SET7/9, TRIM21 could suppress the proliferation, migration, and invasion of breast cancer cells." (PMID 32102992, 2020). "Even though it is not known whether TRIM21 levels are directly decreased by chronic HBV, a previous study revealed that TRIM21 is down-regulated in HCC, colitis-associated cancer, and breast cancer (47, –, 49)." (PMID 38780244, 2024). "Furthermore, compared with their matched adjacent nontumor tissues, the average protein levels of TRIM21 in colorectal and breast cancers were significantly decreased." (PMID 36749630, 2023). "However, it has not been clarified whether TRIM21 functions its role in breast cancer progression through controlling autophagy." (PMID 34001111, 2021). "According to Jin Y.46, TRIM21 could interact with Snail, a master regulator of EMT, and lead to increased ubiquitination degradation of Snail in breast cancer cells MCF-7 and T-47D, these evidences are consistent with us that TRIM21 is a potential tumor suppressor in breast cancer." (PMID 32102992, 2020). "In conclusion, our research provides mechanistic understandings that the negative feedback loops between MTA1 and MTA3, MTA1, and TRIM21 in response to estrogen are initiated to regulate cancer stem cell fate and EMT in breast cancer." (PMID 39154024, 2024). "The subjects with overlapping anti-Ku antibodies and malignancy had melanoma (ARNAP overlap), breast cancer (ACA overlap), and squamous cell skin cancer (ACA and anti-Ro52/TRIM21 overlap), respectively, none of which occurred within 2 years of SSc diagnosis." (PMID 27583908, 2016).
interstitial lung disease (44 papers, 2012 to 2026). A diverse group of lung diseases that affect the lung parenchyma. "Antibodies to Ro52/tripartite motif-containing 21 (TRIM21), referred to as anti-Ro52, are found in patients diagnosed with diverse systemic autoimmune rheumatic disease and associated with interstitial lung diseases." (PMID 35778430, 2022). "Anti-Ro52/TRIM21 antibodies were strongly associated with interstitial lung disease (odds ratio (OR), 1.53; 95% confidence interval (CI), 1.11 to 2.12; P = 0.0091) and overlap syndrome (OR, 2.06; 95% CI, 1.01 to 4.19; P = 0.0059)." (PMID 22394602, 2012). "Anti-TRIM21/Ro52 was previously reported to be associated with interstitial lung disease." (PMID 36982700, 2023). "For example, Ro52/TRIM21 autoantibodies were found to be independently associated with the presence of interstitial lung disease (ILD) and poor survival in SSc, and distinct associations were found for single-specificity anti-PM75, anti-PM100, and anti-PM-1α antibodies." (PMID 27583908, 2016). "In addition, Ro52/TRIM21 appears to have distinct clinical associations in SSc, in particular with interstitial lung disease and overlap syndrome." (PMID 22394602, 2012). "In addition, in this cohort of SSc patients, we found strong suggestions of an association between anti-Ro52/TRIM21 antibodies and interstitial lung disease and overlap syndrome." (PMID 22394602, 2012). "In SSc, anti-Ro52/TRIM21 antibodies may be a marker of interstitial lung disease and overlap syndrome." (PMID 22394602, 2012). "In addition to confirming the serologic associations between anti-Ro52/TRIM21 antibodies and other autoantibodies, we found important associations between anti-Ro52/TRIM21 antibodies, interstitial lung disease, and overlap syndrome." (PMID 22394602, 2012). "In addition, knowing the autoantibody profile of patients may help to predict the possible clinical syndromes that can arise and make clinicians more suspicious for the presence of interstitial lung disease, for instance, when isolated anti-Ro52/TRIM21 exists." (PMID 35871174, 2022). "Unfortunately, this study did not distinguish between anti-Ro60/SSA and anti-Ro52/TRIM21 autoantibodies (the second most common autoantibody observed in SSc cohorts) because the latter have recently been associated with interstitial lung disease in SSc, MCTD, and other CTD." (PMID 27387266, 2016). "Specific signatures such as anti-MDA5 in rapidly progressive interstitial lung disease, anti-RNA polymerase III in scleroderma renal crisis, and anti-Ro52/TRIM21 in systemic overlap syndromes illustrate how serological profiles predict outcomes with remarkable precision." (PMID 41562780, 2026). "In our study, the rate of interstitial lung disease among anti-Ro52/TRIM21 antibody-positive patients was significantly increased by 50% compared with anti-Ro52/TRIM21 antibody-negative patients (OR, 1.53; 95% CI, 1.11 to 2.12; P = 0.0091)." (PMID 22394602, 2012). "Anti-Ro52/TRIM21 antibody-positive patients were more likely to be older (57.16 versus 54.98 years; P = 0.0481), to have interstitial lung disease (44% versus 34%; P = 0.0091), and to have overlap syndrome (22% versus 14%; P = 0.0059) compared with anti-Ro52/TRIM21 antibody-negative patients." (PMID 22394602, 2012).
systemic sclerosis (32 papers, 2009 to 2026). A chronic disorder, possibly autoimmune, marked by excessive production of collagen which results in hardening and thickening of body tissues. "We note that anti-Ro52/TRIM21 in patients with systemic sclerosis are also associated with overlap connective tissue disease features." (PMID 25500701, 2014). "We undertook this study to determine the clinical and serologic associations of anti-Ro52/TRIM21 antibodies in patients with systemic sclerosis (SSc)." (PMID 22394602, 2012). "Nevertheless, anti-Ro52/TRIM21 IgG has clinical utility and may be a useful prognostic marker of severity in a number of SADs such inflammatory myositides and systemic sclerosis." (PMID 35871174, 2022). "Certainly, anti-Ro52/TRIM21 is one of the earliest autoantibodies that emerges years before the onset of disease in systemic sclerosis giving rise to the possibility that Ro52/TRIM21 may be an inciting autoantigen." (PMID 35871174, 2022).